CD163 (CD163 molecule)
Diseases named in the same sentence as CD163 in open-access papers (continued):
Sharing a sentence is not in itself a finding about the gene and the disease.
schwannoma (3 papers, 2022 to 2024). A benign, usually encapsulated slow growing tumor composed of Schwann cells. "CD163+ tumor-associated macrophages in particular have a supportive effect on schwannoma growth." (PMID 36845735, 2023). "CD163: Schwannomas were positive for CD63, with high intensity in all sections, while GCT immunoreactivity was absent." (PMID 35323240, 2022). "The upregulation of CD163 in schwannomas could possibly be explained by a cell phenotype of the spindle cells of schwannomas, similar to the phagocytic phenotype of repair Schwann cells, and also serve as a marker of an inflammatory process." (PMID 35323240, 2022). "CD163 had significantly higher stain intensity in schwannomas (p = 0.00000007)." (PMID 35323240, 2022). "Immunoreactivity to CD68, HLA-DR, CD163, CD40 and CD11c (APC phenotype) and markers of neural crest cell (NCC) origin S100, SOX10, NSE and GAP43 in 23 cases of GCTs and 10 cases of Schwannomas were evaluated." (PMID 35323240, 2022). "In comparison to neural crest schwannomas, myeloid cells in immune-enriched schwannomas accumulated more macrophages lacking CD206 and with lower CD163 expression, a pattern associated with anti-tumor activity." (PMID 38216587, 2024). "This study aims to differentiate an antigen-presenting cell (APC) phenotype from a neural tissue phenotype in GCTs using immunohistochemistry (HLA-DR, CD68, CD163, CD40 and CD11c for APC), and polymerase chain reaction and to compare this expression profile with schwannomas." (PMID 35323240, 2022). "An interesting finding that has not been previously reported was the strong intensity of schwannoma immunoreactivity for CD163." (PMID 35323240, 2022).
scrub typhus (3 papers, 2013 to 2024). Scrub typhus is a rare dust mite-borne infectious disease caused by the Orientia tsutsugamushi bacterium and characterized clinically by an eruptive fever which is potentially serious. "Recently, a paper reported that O. tsutsugamushi mainly infects “inflammatory” CD14/LSP-1/CD68 positive monocytes and CD1a/DCSIGN/S100/FXIIIa and CD163 positive dendritic cells in stained eschar skin biopsies from scrub typhus patients." (PMID 23301113, 2013).
septic shock (3 papers, 2023 to 2025). Shock caused by infection; frequently caused by gram negative bacteria, although some cases have been caused by other bacteria, viruses, fungi, and protozoa; characterized by fever, chills, tachycardia, tachypnea, and hypotension. "Quantitative Reverse Transcription Polymerase Chain Reaction validation was conducted for MMP8, MMP9, ARG1, HP, and CD163 across healthy controls, SIRS, and septic shock patient groups." (PMID 39560539, 2024). "Finally, the key genes CD163, MCEMP1, and RETN were discovered in septic shock, which is expected to provide new insights into the pathogenesis of septic shock." (PMID 40599778, 2025). "In Kjærgaard’s study, the expression of CD163 monocytes in non-surviving patients with septic shock was higher than that of surviving patients at ICU admission and surviving patients during observation." (PMID 40599778, 2025).
soft tissue sarcoma (3 papers, 2021 to 2023). A malignant neoplasm arising from muscle tissue, adipose tissue, blood vessels, fibrous tissue, or other supportive tissues excluding the bones. "The discrepancy found with soft tissue sarcomas, in which CD163+ macrophages dominate over CD68+ macrophages, could be explained by the fact that CD68 is not only a macrophage-marker, but also, in the context of bone tissue, a marker of osteoclastic cells." (PMID 33498676, 2021). "In this study, we subjected surgical specimens of 75 soft-tissue sarcomas to immunohistochemical examination and counted the number of the infiltrating CD68-positive macrophages (total macrophages) and CD163- and CD204-positive macrophages (TAMs)." (PMID 36690825, 2023). "The number of CD68-, CD163-, and CD204-positive macrophages in the intratumoral and marginal areas of 75 soft-tissue sarcoma specimens was counted." (PMID 36690825, 2023).
spondyloarthritis (3 papers, 2013 to 2017). "This hypothesis is supported by a previous immunostaining study showing enhanced accumulation of CD163+ macrophages in the intestinal mucosa of patients with CD and patients with spondyloarthropathy." (PMID 23922818, 2013).
vasculitis (3 papers, 2016 to 2021). "CD163 as a marker of macrophages has innate advantages in deepening our understanding of vasculitis." (PMID 33997033, 2021). "As we know, this is the first research to determine the concentration of urinary CD163 levels in various vasculitis." (PMID 33997033, 2021). "In our study, we found that urinary CD163 concentrations were significantly elevated in patients with vasculitis when compared to healthy controls." (PMID 33997033, 2021). "Previous studies have shown that urinary excretion of soluble CD163 (sCD163) is a biomarker of macrophage activation in rats with experimental vasculitis and in patients with small vessel vasculitis and lupus nephritis." (PMID 31053735, 2019). "Therefore, we aim to investigate the concentration of urinary CD163 in patients with different types of vasculitis and relate this measurement to clinical parameters." (PMID 33997033, 2021). "Therefore, the previous studies of urinary CD163 levels in vasculitis mainly focused on AAV." (PMID 33997033, 2021). "To explore the changes of urinary CD163 in patients with vasculitis who have renal involvement, we divided vasculitis into two groups: renal involvement and nonrenal involvement." (PMID 33997033, 2021). "It suggested that CD163 was not a specific indicator of AAV, and CD163 may be also involved in the pathogenesis of other vasculitis, such as TA, BD, and GCA, but not PAN." (PMID 33997033, 2021). "In our result, patients with AAV have the trend of increasing CD163 levels, but not showing statistical difference between subgroups of vasculitis, and it may relate to the great disparity in the number of the two groups (18 vs. 35) and small sample size." (PMID 33997033, 2021). "However, to our knowledge, urinary CD163 levels in patients with other subtypes of vasculitis have not been studied." (PMID 33997033, 2021).
Wilson disease (3 papers, 2018 to 2022). A very rare inherited multisystemic disease presenting non-specific neurological, hepatic, psychiatric or osseo-muscular manifestations due to excessive copper deposition in the body. "The macrophage activation marker soluble (s)CD163 is associated with severity and prognosis in a number of different acute and chronic liver diseases but has been only sparsely examined in Wilson’s disease (WD)." (PMID 32615997, 2020).
abortion (2 papers, 2019 to 2024). the ending of pregnancy by removing a fetus or embryo before it can survive outside the uterus. "In a previous study the A allele of CD163-rs1107556229 was associated with a lower probability of abortion during PRRSV outbreaks." (PMID 39696499, 2024). "Recently, PRRSV-induced abortion was attributed to fetal placental and endometrium epithelial cells (Sn+ and CD163+) apoptosis." (PMID 31426793, 2019).
acute appendicitis (2 papers, 2024 to 2025). "The increase in the number of CD68-positive cells and CD163-positive cells (macrophages) in both groups with acute appendicitis may indicate containment of the infectious agent or an undesirable effect of an inflammatory reaction based on immune system dysregulation." (PMID 38397914, 2024). "In our series, in the appendiceal mucosa, macrophages cell rate (CD163+), T helper lymphocytes (CD4+), T cytotoxic lymphocytes (CD8+) and activated cytotoxic lymphocytes (CD8+CD69+) were all significantly lower in UC patients compared to appendicitis and CC patients." (PMID 40827526, 2025).
arthropathy (2 papers, 2015 to 2021). Any disorder of the joints. "This study revealed that, in the IFP of arthropathy patients, abundant CD14-positive cell stores and the ratio of CD14++CD80+ cells/CD14++CD163+ cells were elevated, implying the localization of inflammation in the IFP." (PMID 34899727, 2021).
benign prostatic hyperplasia (2 papers, 2020 to 2024). A non-cancerous nodular enlargement of the prostate gland. "In the early stages of benign prostatic hyperplasia, CD68(+)CD163(+) anti-inflammatory macrophages are converted to the myofibroblast phenotype and promote stromal fibrotic tissue remodeling." (PMID 39261656, 2024).
bullous pemphigoid (2 papers, 2018 to 2022). Bullous pemphigoid (BP) is the most common form of autoimmune bullous dermatosis. "Histologically, CD163+ M2 macrophages are prominent in the lesional skin of bullous pemphigoid, and soluble (s)CD163 is increased in serum from patients with bullous pemphigoid compared to healthy donors." (PMID 36555362, 2022).
Cachexia (2 papers, 2023 to 2025). Severe weight loss, wasting of muscle, loss of appetite, and general debility related to a chronic disease. "At the time of cachexia onset (D12), when we first observed fibre atrophy and ECM expansion, upregulated genes showed enrichment of pathways related to ECM remodelling and fibrosis and included markers for anti‐inflammatory M2 macrophages (Cd163) which are linked to tissue and organ fibrosis." (PMID 39810606, 2025).
cervical squamous cell carcinoma (2 papers, 2017 to 2021). A squamous cell carcinoma arising from the cervical epithelium. "A previous report analyzing cervical squamous cell carcinomas revealed that many intratumoral Gal3 expressing cells are CD163 positive M2 polarized macrophages." (PMID 29284429, 2017).
cervical tumor (2 papers, 2014 to 2024). "Our observations strongly suggest that the effect on CD163 expression is specific to CC cells, as is the existence of soluble factors secreted by cervical tumor cells, but not by nontumorigenic cells implicated in polarization into M2 macrophages." (PMID 25309919, 2014).
chondrosarcoma (2 papers, 2021 to 2023). A malignant cartilaginous matrix-producing mesenchymal neoplasm arising from the bone and soft tissue. "CD163+ macrophages were also identified in another cohort of 26 grade 1–3 conventional chondrosarcomas and were localized mainly at the peripheral site of the tumor." (PMID 37958467, 2023). "Furthermore, the highest CD163+ M2 macrophage density was found in the highest grade of chondrosarcoma, suggesting the involvement of M2 macrophages in tumor progression through its role in angiogenesis, migration, or invasion." (PMID 37958467, 2023). "Chondrosarcomas have demonstrated CD163+ macrophage infiltration, which has been associated with more invasive and higher-grade chondrosarcomas, while higher concentrations of CD8+ T cells have shown to repress chondrosarcoma progression." (PMID 34067530, 2021).
chronic B hepatitis infection (2 papers, 2020 to 2024). "When CD163 expression was evaluated, a broader expression in C compared to NC monocytes was demonstrated, similar to what was observed in chronic B hepatitis infection." (PMID 39766068, 2024).
chronic hepatitis (2 papers, 2012 to 2013). An active inflammatory process affecting the liver for more than six months. "The serum CD163 levels increased as the procession of chronic hepatitis, indicating the activation of macrophages, which was consistent with the PH patients." (PMID 23118797, 2012). "It was y = 22.8210x + 19.3530 (R = 0.9889, P < 0.01) from the AUCs to the serum CD163 levels at d28, d56, and d84 in the progression of CCl4-induced chronic hepatitis." (PMID 23118797, 2012). "The serum CD163 levels were increased gradually from d0 to d84 (P < 0.01) as the procession of chronic hepatitis." (PMID 23118797, 2012). "The liner regressive equation was y = 0.8531x + 26.2360 (R = 0.7838, P > 0.05) from the AUCs of Sal B to the serum CD163 levels at d0, d28, d56, and d84 in the progression of CCl4-induced chronic hepatitis." (PMID 23118797, 2012). "Both plasma sCD163 and peritumoral infiltrated CD163+ cells could be the indicators of chronic hepatitis." (PMID 23555776, 2013).
chronic pancreatitis (2 papers, 2021 to 2024). A chronic inflammatory process causing damage and fibrosis of the pancreatic parenchyma. "As we anticipated, the mRNA expression levels of CCL5 and M2 marker CD163 were negatively correlated with the protein level of UBE2M, suggesting the neddylation-associated modulation of macrophages in chronic pancreatitis." (PMID 33723230, 2021). "Compared with normal healthy controls, UBE2M is remarkably decreased in human chronic pancreatitis tissues accompanied by increased CCL5 and CD163 (markers of M2-type macrophages), indicating the important role of NEDDylation in the pathogenesis of chronic pancreatitis." (PMID 39697538, 2024).
complication (2 papers, 2013 to 2022). Any disease or disorder that occurs during the course of, or because of, another disease, treatment, or procedure. "The central role of Hp in complexing free Hb and mediating its clearance through CD163 led us to consider whether the Hp2-2 genotype, clinically associated with cardiovascular complications, may show impaired anti-inflammatory signaling engagement downstream of CD163." (PMID 23710416, 2013). "Clinical studies have demonstrated a correlation between impaired scavenging of Hb-Hp complexes via CD163 and diabetic vascular complications." (PMID 35163309, 2022).
cyst (2 papers, 2022). A sac-like closed membranous structure that may be empty or contain fluid or amorphous material. "Indeed, we found that 99% of IBA1+-cells co-expressed CD163 by week 10 in the 3D-cyst." (PMID 35789843, 2022).
cystic tumors (2 papers, 2019 to 2020). "Furthermore, the expression of M-CSF as well as the number of CD-163 positive macrophages appears to be higher in cystic tumors." (PMID 30580386, 2019). "Finally, cystic tumors showed a significantly higher degree of CD-163 expression compared to non-cystic tumors (p = 0.005)." (PMID 30580386, 2019).
dendritic cell neoplasms (2 papers, 2023 to 2024). "The 5th edition of the WHO Classification of Hematolymphoid Tumors subcategorizes the dendritic cell neoplasms under the spectrum of histiocytic/dendritic cell neoplasms based on their histogenesis and their distinct immunophenotypic profile (positive for CD45, CD4, CD68, CD163, and lysozyme)." (PMID 39592527, 2024).
diffuse midline glioma (2 papers, 2024). A diffuse glioma that arises from the midline structures of the central nervous system. "While the percentage of tumor-associated CD68+ macrophages is comparable across subgroups, diffuse midline gliomas have the lowest number of infiltrating CD8+ T cells and CD163+ macrophages, which contributes to their immunosuppressive phenotype." (PMID 38542199, 2024). "This hypothesis-generating study characterized the mRNA expression profiles and prognostic impacts of antigen-presenting cell (APC) markers (CD14, CD163, CD86, and ITGAX/CD11c) in pediatric brainstem diffuse midline glioma (pbDMG) tumors." (PMID 38255296, 2024).
ductal carcinoma (2 papers, 2012 to 2023). "CD68+ and CD163+ macrophages were found to be enriched in the invasive front of luminal ductal carcinomas." (PMID 37756565, 2023). "In order to obtain insights into the nature of FOXP3+ cells associated with favorable prognosis in ductal carcinoma, TMA slides were stained with anti CD3 and anti CD163 Abs." (PMID 22471961, 2012).
End Stage Liver Disease (2 papers, 2021 to 2022). Final stage of a liver disease when the liver failure is irreversible and LIVER TRANSPLANTATION is needed. "Increased baseline model for end-stage liver disease score, white cell count, calprotectin, CD163, tumor necrosis factor, renin, atrial natriuretic peptide, and syndecan-1 were associated with 3-month mortality." (PMID 35333783, 2022). "Patients who died within 3 months of trial entry had significantly higher model for end-stage liver disease (MELD) score, serum white cell count, CD163, and TNFα at baseline compared with those who survived." (PMID 35333783, 2022).
endometritis (2 papers, 2023 to 2025). An acute or chronic, usually bacterial infectious process affecting the endometrium. "First, the population profile of CD163+ macrophages was maximal in patients with mild chronic endometritis and decreased in patient groups with more severe endometritis." (PMID 41511322, 2025).
enthesitis (2 papers, 2020 to 2023). Inflammation at the site of insertion of ligaments, tendons, and other fibrous structures into bone. "Additionally, CD163 positive monocytes have been described in the joint of enthesitis-related JIA, but not oJIA." (PMID 37283752, 2023). "Interestingly, we could not detect any increase in CD163 neither on the surface- nor at mRNA level in our oligoarticular JIA patients, but has previously been observed in enthesitis-related JIA." (PMID 32787920, 2020).
esophageal tumor (2 papers, 2020 to 2021). "In addition, compared with normal tissues, the expression of CD163 was significantly increased in EC tissues, indicating a greater population of M2 macrophages in esophageal tumors." (PMID 34561425, 2021). "We performed a correlation analysis of various macrophage markers in esophageal tumor and demonstrated that PU.1 expression strongly correlates with that of CD68 (r = 0.833, p ≤ 0.001), CD163 (r = 0.500, p ≤ 0.001), and CD206 (r = 0.250, p = 0.043) with the strongest correlation observed for CD68." (PMID 32884895, 2020).
extramammary Paget disease (2 papers, 2020 to 2023). A malignant neoplasm in which there is infiltration of the skin by neoplastic large cells with abundant pale cytoplasm and large nuclei with prominent nucleoli (Paget cells). "In extramammary Paget’s disease high levels of Staphylococcus aureus were detected that coincided with CD163-positive M2-like macrophages, whereas potential association of Shewanella, V. parahaemolyticus, and Microbacterium sp." (PMID 36999042, 2023).
gallbladder cancer (2 papers, 2022 to 2024). "The expression levels of CD68 and CD163 in M2-like TAMs and CD44 and CD133 in gallbladder cancer stem cells (GBCSCs) were increased and positively correlated in GBC tissues compared with those in neighboring noncancerous tissues." (PMID 39138521, 2024). "The highest levels of CD163+ TAM is found to correlate with the shortest five-year relative survival rates in pancreas, lung and gallbladder cancers." (PMID 36605202, 2022).
Glucose intolerance (2 papers, 2017 to 2019). Glucose intolerance (GI) can be defined as dysglycemia that comprises both prediabetes and diabetes. "Here we aim to investigate soluble CD163 (sCD163) and soluble tumour necrosis factor-like weak inducer of apoptosis (sTWEAK) in early pregnancy GDM and their association to the development of later glucose intolerance." (PMID 31071174, 2019).
hemangioma (2 papers, 2021 to 2024). A benign vascular lesion characterized by the formation of capillary-sized or cavernous vascular channels. "LCA is sometimes positive for transferrin receptors compared with other hemangiomas, which also shows positive staining for endothelial cells and tissue cells, such as factor VIII(+), CD31(+), CD163(+), CD68(+), and CD21(+)." (PMID 39544335, 2024). "Highest numbers of CD163+ cells were detected in liver samples from patients diagnosed with HCC (D05 and D09) and in tissue sample from patient D15 with hemangioma." (PMID 33918803, 2021).
hepatitis B (2 papers, 2014 to 2018). "We assessed the expression of CD163 on monocytes from both circulating cells and the liver tissues of patients with hepatitis B induced liver failure using flow cytometry and isolated the myofibroblasts from diseased livers." (PMID 24597777, 2014). "We discovered that CD163 is highly expressed on monocytes in liver tissues and in the circulation of patients with hepatitis B induced liver failure, indicating that CD163+ monocytes could be involved in the pathogenesis and clinical course of liver failure." (PMID 24597777, 2014).